RNU2-71P (RNA, U2 small nuclear 71, pseudogene)
Gene: Small nuclear RNA gene on chromosome 8 (80,585,585 to 80,585,773, reverse strand). Ensembl gene ENSG00000223327.
Homologues: Orthologues: chimpanzee U2 (98% identical), macaque U2 (92% identical), dog U2 (76% identical), pig U2 (76% identical), tropical clawed frog U2 (43% identical), rabbit U2 (38% identical), guinea pig U2 (35% identical). Paralogues in human: RNU2-59P (80% identical), U2 (80% identical), U2 (79% identical), RNU2-61P (77% identical), RNU2-6P (77% identical), RNU2-64P (77% identical), RNU2-2 (76% identical), RNU2-4P (76% identical), RNU2-26P (75% identical), RNU2-3P (75% identical), RNU2-57P (75% identical), RNU2-14P (74% identical), and 66 more.